CD6 (CD6 molecule)
Diseases named in the same sentence as CD6 in open-access papers (continued):
Sharing a sentence is not in itself a finding about the gene and the disease.
experimental autoimmune encephalomyelitis (7 papers, 2017 to 2025). An autoimmune demyelinating disease of the central nervous system that is produced experimentally in animals by the injection of homogenized brain or spinal cord in Freund's adjuvant. "In our previous studies of experimental autoimmune encephalomyelitis (EAE), an animal model of MS, we found that CD6-KO mice were protected, as indicated by reduced T cell infiltration and inflammation in the CNS." (PMID 35951427, 2022). "Thus, CD318–/– mice reproduced the phenotype of attenuated disease seen in CD6–/– mice in the mouse experimental autoimmune encephalomyelitis (EAE) model of MS, but mice lacking CD166 experienced exacerbation of EAE." (PMID 33497367, 2021).
uveitis (7 papers, 2022 to 2025). An inflammatory process affecting a part of or the entire uvea. "We then tested the efficacy of the CD6-ADC in preventing the development of uveitis induced by the adoptive transfer of preactivated uveitogenic T cells." (PMID 37917882, 2023). "A single dose of CD6-ADC suppresses the development of uveitis induced by an adoptive transfer of preactivated uveitogenic T cells." (PMID 37917882, 2023). "In these studies, CD6−/− mice with EAU had significantly decreased retinal inflammation and reduced autoreactive T cell responses, indicating that CD6-targeted therapies are a promising new treatment for uveitis." (PMID 36275816, 2022). "CD6-ADC reverses the progress of uveitis induced by active immunization." (PMID 37917882, 2023). "Taken together, these data indicate strongly that CD6 on T cells might interact with its receptors, such as CDCP1, on the BRB to facilitate retinal infiltration and uveitis development." (PMID 35951427, 2022).
autoimmune uveitis (6 papers, 2021 to 2025). An autoimmune form of uveitis (disease). "Polymorphisms in CD6 have been associated with multiple sclerosis (MS) and autoimmune uveitis, which both share an integral role for autoreactive T cells in pathogenesis." (PMID 35951427, 2022). "We also tested its treatment efficacies in 2 preclinical models of autoimmune uveitis using our CD6-humanized mice and a humanized model of GVHD using NOD/SCID IL-2 receptor γ–/– (NSG) mice." (PMID 37917882, 2023). "In summary, the CD6-ADC selectively kills proliferating pathogenic T cells and is highly effective in treating 2 preclinical models of autoimmune uveitis as well as a humanized model of GVHD even when given at a low dose." (PMID 37917882, 2023). "More importantly, the CD6-ADC was highly effective in treating 2 preclinical models of autoimmune uveitis and a humanized model of GVHD, in all of which antigen-specific T cells cause the pathology." (PMID 37917882, 2023). "These intriguing results suggest that the CD6-ADC holds promise as a drug for treating pathogenic T cell–mediated disorders, including but not limited to diseases like autoimmune uveitis, MS, RA, GVHD, and transplantation rejections." (PMID 37917882, 2023). "The function of CD6 as a negative regulator of T cell activation during mCoV encephalomyelitis stands in stark contrast to its co-stimulatory role in multiple autoimmune models including autoimmune encephalitis and autoimmune uveitis." (PMID 39679790, 2025). "Additionally, we tested the treatment efficacy of the CD6-ADC in an autoimmune uveitis model induced by active immunization with progressive disease." (PMID 37917882, 2023). "All these experiments showed that treatment of CD6-ADC substantially eliminated the pathogenic human T cells and attenuated GVHD in mice, suggesting that the CD6-ADC can be used to treat T cell–mediated disorders such as GVHD in additional to autoimmune uveitis." (PMID 37917882, 2023). "Furthermore, in vivo, whereas the CD6-ADC had no significant detrimental effect on normal T cells in naive CD6-humanized mice, the same dose of CD6-ADC, but not the controls, efficiently treated 2 preclinical models of autoimmune uveitis and a model of graft versus host disease." (PMID 37917882, 2023).
Behçet’s disease (6 papers, 2017 to 2024). "Several CD6 SNPs have been associated to immune-mediated inflammatory disorders, including MS, Ps and Behçet’s disease." (PMID 34070159, 2021).
Arthritis (5 papers, 2022 to 2025). Inflammation of a joint. "CD6−/− mice develop lower clinical arthritis scores than wildtype (WT) mice, proving that CD6 can tune the severity of joint inflammation in these mice." (PMID 36275816, 2022). "Specifically, future studies ought to be evaluated through targeted anti-CD6 inhibitors in TNF-Tg mice, or through genetic ablation of CD6 by crossing CD6-KO with TNF-Tg cohorts, to investigate endpoints such as arthritis severity and IgG2b+ plasma cell accumulation in downstream PLNs." (PMID 37691918, 2023).
diabetes (5 papers, 2022 to 2025). "These clustered 7 proteins also showed some weak-to-moderate positive correlations with the remaining 11 proteins, including 3 proteins that were inversely associated with diabetes (CD6, CXCL10, and TWEAK)." (PMID 38643166, 2024). "Although administration of anti-CD6 antibodies in combination with oral insulin was shown to be protective of diabetes in new onset diabetes in mice, the function of CD6 in monocytes has not been described." (PMID 35851422, 2022). "Our results also revealed that another five proteins (HGF, CD6, fibroblast growth factor 21 (FGF-21), LIF-R, and OSM) might mediate the associations of gut bacteria with diabetes." (PMID 38643166, 2024). "For another eight biomarkers (TNFβ, GDNF, IL-18R1, LIF-R, CD244, CD6, FGF-5, IFNγ), a significant interaction by diabetes type was observed." (PMID 39799156, 2025). "The use of a combined treatment involving anti-CD6 therapy and oral insulin immunization effectively reverses recent-onset diabetes in non-obese diabetic mice." (PMID 39170074, 2024).
lupus (5 papers, 2017 to 2024). "Blocking CD6 in murine lupus resulted in significant reductions in immune cell infiltration and amelioration of nephritis." (PMID 38899167, 2024). "CD6 blockade in models of spontaneous lupus and immune-complex glomerulonephritis revealed significant decreases in immune cells, inflammatory markers, and disease measures." (PMID 34981775, 2022). "Given the increased expression of CD6 and ALCAM in MRL/lpr mice, we evaluated the role of CD6/ALCAM in lupus by blocking the pathway using a mouse CD6-specific monoclonal antibody (anti-CD6)." (PMID 34981775, 2022). "In mouse models of lupus, blockade of CD6 with an anti-mouse CD6 monoclonal antibody decreases T cell infiltration, cytokine levels and overall renal pathology." (PMID 36275816, 2022). "Treatment with anti-CD6 led to improved renal function in mice with spontaneous lupus." (PMID 34981775, 2022). "In conclusion, the data from MLR and cGvHD-induced lupus-like models in CD6−/− mice illustrate the relevance of CD6 in T (and B) cell proliferative responses and, even more importantly, Treg induction and suppressive function in the in vivo maintenance of peripheral tolerance." (PMID 28611770, 2017). "T cells and monocytes isolated from spleens of the lupus mouse strains exhibited similar but smaller increases in both CD6 and ALCAM compared with C567BL/6 mice, suggesting that this pathway may be important both for systemic autoimmunity and end organ disease." (PMID 34981775, 2022). "When CD6 expression was examined, CD6 and CD3 coexpressing cells (stained yellow) were noted in both the kidneys and spleens of lupus mice, with these being more frequent than those seen in control C57BL/6 mice." (PMID 34981775, 2022). "Interestingly, the lupus spleens also exhibited cells that were discordant for CD3 and CD6 expression, stained green or red, respectively." (PMID 34981775, 2022).
Sjögren's syndrome (5 papers, 2017 to 2024). "Lower CD6+ memory B cells in patients with primary Sjogren’s syndrome (pSS), was reported to be due to the transmigration of CD27+ memory B cells into salivary glands of pSS patients." (PMID 39026665, 2024). "Logistic regression analyses of CD5 and CD6 SNPs association with anti-Ro/La antibodies, neutropenia, leukopenia, and peripheral nervous system (PNS) EULAR Sjögren's syndrome disease activity index (ESSDAI) activity." (PMID 35372412, 2022).
atherosclerosis (4 papers, 2011 to 2024). A disease characterized by the build-up of fatty material and calcium deposition in the arterial wall resulting in partial or complete occlusion of the arterial lumen. "A potential way to address this limitation in future studies could be to use anti-CD6 neutralizing antibody treatment in an inbred mouse model of atherosclerosis." (PMID 29615096, 2018). "We generated the double knockout (DKO) mouse model of CD6 deficiency (CD6−/−) and apolipoprotein E deficiency (apoE−/−) on the DBA atherosclerosis-sensitive genetic background in order to determine if CD6 expression is atheroprotective due to increased production of natural IgM." (PMID 29615096, 2018). "Thus, loss of CD6 on lymphocytes did not lead to expected reductions in B1a cells and protective IgM levels, and in turn did not alter atherosclerosis in mice." (PMID 29615096, 2018). "Surprisingly, some markers of atherosclerosis (fractalkine/CX3CL1, CCL8, M-CSF, HGF), T-cell development/activation (CD40L, IL-7, CCL25, IL-2RB, IL-15RA, CD6) and angiogenesis (VEGF-A) were significantly increased only in AD." (PMID 28821884, 2017). "In contrast, the individuals with atherosclerosis in our study demonstrated a reduction in the expression of genes which contribute to T cell activation and maturation (CD3, CD3E, CD6, CD27)." (PMID 21698167, 2011). "Notably, these correlations might suggest a link between the metabolome and protein markers related to immune signalling (LTα, CD6, CCL21, SELE), energy balance and metabolism-related hormones (IGFBP1, SHGB, ADM, leptin, and STC1), and atherosclerosis/thrombosis inhibitor (PAI1)." (PMID 39154540, 2024). "Thus, the lack of altered atherosclerosis in the DKO mice indicates that CD6 therapeutic potential may not extend to cardiovascular-related disease." (PMID 29615096, 2018).
influenza (4 papers, 2015 to 2025). An acute viral infection of the respiratory tract, occurring in isolated cases, in epidemics, or in pandemics; it is caused by serologically different strains of viruses (influenzaviruses) designated A, B, and C, has a 3-day incubation period, and usually lasts for 3 to 10 days. "To evaluate the potential of mAb CD6 to protect against influenza, we monitored weight loss and survival of DBA/2 mice infected with 10 median lethal doses (LD50) of CA/09-X179A either before or after CD6 treatment." (PMID 25668439, 2015). "A total of 7,789 patients with laboratory-confirmed influenza were identified when including diagnoses from CD1 to CD6." (PMID 40843520, 2025).
prostate carcinoma (4 papers, 2021 to 2024). A carcinoma that arises from epithelial cells of the prostate gland. "Here we demonstrate that disrupting the CD6-CD318 axis with UMCD6, an anti-CD6 monoclonal antibody, prolongs survival of mice in xenograft mouse models of human breast and prostate cancer, treated with infusions of human lymphocytes." (PMID 38280067, 2024). "In vitro killing of breast and prostate cancer cells is enhanced by mAbs to CD6 or CD318." (PMID 33497367, 2021). "Co-culture experiments using breast, lung, and prostate cancer cell lines showed substantial enhancement of cancer cell death in the presence of human lymphocytes and UMCD6, an anti-CD6 monoclonal antibody that rapidly caps and internalizes CD6." (PMID 39840036, 2024). "In vivo, targeting the interaction between CD6 and its ligand CD318 with UMCD6 increases survival of breast and prostate cancer xenografted mice that also receive infusions of human lymphocytes." (PMID 39840036, 2024). "In this study, we performed gene expression analysis on peripheral blood from prostate cancer patients obtained post- radiotherapy and showed that 6 genes, including CCR7, FCGR2B, BTLA, CD6, CD3D, and CD3E, were down-regulated by a range of 1.5–2.5-fold as compared to pre-radiotherapy samples." (PMID 36291815, 2022). "In this study, we performed next-generation sequencing-based gene expression analysis in peripheral blood from prostate cancer patients obtained pre- and post-radiotherapy and found six independently down-regulated genes including CCR7, FCGR2B, BTLA, CD6, CD3D, and CD3E." (PMID 36291815, 2022).
asthma (3 papers, 2022 to 2025). "Similarly to CD6-deficient mice, ALCAM-deficient mice were found to develop a reduced T cell response in vivo, as recently demonstrated in mouse models of asthma, atopic dermatitis, and food allergies." (PMID 37514028, 2023).
B-cell chronic lymphocytic leukemia (3 papers, 2010 to 2024). "The protective effect of CD6 expression on TCR-induced apoptosis would agree with previous reports showing that CD6 ligation prevents IgM cross-linking-induced apoptosis of leukemic B cells (chronic lymphocytic leukemia)." (PMID 28713387, 2017). "Hematopoietic precursors thymocytes, mature T and NK cells, a subset of normal B lymphocytes and most of those from lymphocytic chronic leukemia (CLL) transcribe mRNAs for CD6." (PMID 22076177, 2010). "In patients with B-cell chronic lymphocytic leukemia (CLL), CD6 is also expressed on a significant proportion of their malignant B cells." (PMID 39840036, 2024).
lung carcinoma (3 papers, 2023 to 2025). "For example, we observed a CD6-ALCAM signaling pathway existing between DC (source) and TRM CD4+ T cells (target) in the lung cancer tumor microenvironment (TME)." (PMID 36810839, 2023). "UMCD6—an mAb targeting the CD6/CD318 axis—enhances the ability of CD8+T, NK-T, and NK cells to kill breast, prostate, and lung cancer cells, accompanied by robust changes in gene and protein expression of the activating receptor NKG2D and the inhibitory receptor NKG2A." (PMID 39996744, 2025). "In addition, recent research has shown that targeting the CD6/CD318 axis with the mAb UMCD6 (anti-CD6) increases cytotoxic-lymphocyte-mediated cancer cell death of breast, prostate, and lung cancers both in vitro and in vivo." (PMID 39996744, 2025).
virus infection (3 papers, 2015 to 2025). "We therefore sought to characterize how CD6 regulates T cell activation in the context of viral infections using an in vivo murine coronavirus model." (PMID 39679790, 2025). "The number of ongoing clinical trials examining the efficacy of CD6 blockade necessitates further interrogation of its role during viral infections and vaccination, especially given the context-dependent role of CD6 in T cell activation." (PMID 39679790, 2025). "Given the ability of CD6 to carry out opposing functions, this study sought to determine how CD6 regulates early T cell activation in response to viral infection." (PMID 39679790, 2025). "Given that CD6 conversely supports CD4 T cell activation in many autoimmune models, we probed potential mechanisms of CD6-mediated suppression of CD4 T cell activation during viral infection." (PMID 39679790, 2025). "Our results demonstrate that CD6 acts as a negative regulator of CD4 T cell activation in CNS draining cLN following virus infection." (PMID 39679790, 2025). "Elevated expression of CD6 on CD8+ T-cells following viral infection is consistent with previous in vitro studies addressing the effect of TCR crosslinking on CD6 expression." (PMID 31998302, 2019). "Overall, our data provide novel insights into the in vivo dynamics of CD6 cell surface expression on CD8+ T-cells in different tissue compartments following viral infection." (PMID 31998302, 2019). "Although, PD-1 is rapidly upregulated on CD8+ T-cells in vivo following viral infection, studies on expression kinetics of CD6 on activated CD8+ T-cells in vivo are limited." (PMID 31998302, 2019). "CD6 inhibited the drug-resistant virus at very low concentrations (IC50: 28±10 ng ml−1), highlighting the potential of the CD6 epitope to serve as a target for alternative antibody therapeutics against pH1N1 virus infection." (PMID 25668439, 2015). "The dual functions of CD6 as a positive and a negative regulator of T cell activation are well established, but its influence on T cell responses during viral infections has not been studied." (PMID 39679790, 2025).
colitis (2 papers, 2015 to 2022). Inflammation of the colon. "The observation that both CD5- and CD6-deficient mice differ in their response to DSS-induced colitis further supports their involvement in IBD." (PMID 36211446, 2022). "The CD6 rs17824933GG genotype was also associated with higher extent (left or extensive colitis) in UC patients." (PMID 36211446, 2022). "To this end, we first analyzed the impact of Cd5 and Cd6 deficiency on dextran sulphate sodium (DSS)-induced colitis, an experimental model of human IBD." (PMID 36211446, 2022). "We have observed seasonal variations also for Cd6-/- mice regarding susceptibility to DSS-induced colitis." (PMID 36211446, 2022). "Here we observed that Cd6-/- mice exhibit an increased body weight loss and DAI upon DSS-colitis induction, in conjunction with differential expression of certain mRNA transcripts." (PMID 36211446, 2022). "The two mouse lines showed opposite results regarding body weight loss and disease activity index (DAI) changes following DSS-induced colitis, thus supporting Cd5 and Cd6 expression involvement in the pathophysiology of this experimental IBD model." (PMID 36211446, 2022). "Additionally, reduced mRNA expression of Ncr1 —coding for NKp46, one of the NK triggering receptors— and a trend towards increased Lcn2 —coding for lipocalin-2, also named NGAL, a neutrophil secondary granule marker— in colons of Cd6-/- mice undergoing DSS-induced colitis was observed." (PMID 36211446, 2022). "The putative role of CD5 and CD6 lymphocyte co-receptors in the pathophysiology of IBD was first explored by subjecting Cd5-/- and Cd6-/- mice to the DSS-induced colitis." (PMID 36211446, 2022). "More precisely, the exacerbated DSS-induced colitis phenotype of Cd6-/- mice manifested during the spring/summer but not the autumn/winter season, reminiscent of other mouse models of human diseases (i.e., EAE)." (PMID 36211446, 2022). "Contrary to the Cd5-/- case, the lack of published information of Cd6-/- mice on the DSS-induced colitis model encouraged a deeper evaluation of different experimental parameters at the end of disease follow-up (day 8)." (PMID 36211446, 2022).
H1N1 influenza (2 papers, 2015 to 2022). "It would be expected that other NA inhibitory mAbs such as 1G01 or CD6 would also be able to reduce H1N1 virus infection of HAE cells." (PMID 35100294, 2022).
immune deficiencies (2 papers, 2018 to 2022). "Six genes related to (a) immune checkpoints (n = 2; BTLA and CD6); (b) regulatory macrophages and T cells (n = 2; CCR7 and CD3D); and (c) immune deficiencies and unfavorable prognosis (n = 2; CD3E and FCGR2B) were down-regulated post-RT compared with pre-RT (statistical p-range: <0.0001–0.0415)." (PMID 36291815, 2022).
ischaemic stroke (2 papers, 2022 to 2024). "TFPI, CD40, IL6RA and MMP12 were associated with a lower risk of any stroke and any ischaemic stroke, while TMPRSS5 and CD6 was associated with a higher risk of any stroke." (PMID 36253349, 2022). "Similarly, CD6 pQTLs colocalized with any stroke genetic associations; CD40 pQTLs colocalized with the genetic associations for any stroke, any ischaemic stroke and large artery stroke; TMPRSS5 pQTLs colocalized with any stroke, any ischaemic stroke and cardioembolic stroke genetic associations." (PMID 36253349, 2022).
melanoma (2 papers, 2022 to 2025). A malignant, usually aggressive tumor composed of atypical, neoplastic melanocytes. "Lower frequencies of CD6+ cells in PBMCs correlate with worse progression-free survival and overall survival in patients with non-small cell lung cancer and melanoma." (PMID 40391211, 2025).